PTGER4 (prostaglandin E receptor 4)
Diseases named in the same sentence as PTGER4 in open-access papers (continued):
Sharing a sentence is not in itself a finding about the gene and the disease.
tumor (continued). "Furthermore, higher PTGER4 expression was maintained in PTGER4 tumour xenografts compared with xenografts from WT cells indicating that stability of the transgene was maintained throughout the duration of the experiment." (PMID 21589857, 2011). "TNM staging is inextricably linked to tumour formation, progression and regression, with stage IV patients having the most advanced disease, resulting in hypermethylation of the promoter regions of oncogenes such as SHOX2 and RASSF1A and hypomethylation of the proto-oncogene PTGER4 gene." (PMID 40386526, 2025). "RNA-seq analysis of YFP+ tumor cells sorted from s.c. implanted tumors revealed a decrease in transcript counts for genes encoding 3 adenosine-synthesizing enzymes, CD73, CD38, and CD203a, and an increase in CD39 transcript counts, in Ptges-KO and Ptger4-KO tumors." (PMID 39298269, 2024). "Most recently, via using mPGES1-deficient mice, PTGER4-deficient mice and specific antagonists of EPs, a study from Inada’s laboratory assessing the role of PGE2 in the soft tissue tumors revealed that PGE2 acted on fibroblasts in tumor microenvironment through EP4 receptor." (PMID 31063976, 2019). "Prostaglandin E receptor 4 (PTGER4), a member of the G protein-coupled receptor family, functions as a significant tumor suppressor." (PMID 40666096, 2025). "In addition to the changes in TME, the analysis of tumor-draining lymph nodes revealed increased proportions of Ki67+ proliferative CD8+ and CD4+ T cells in Ptger4-KO tumor–bearing mice, suggesting that the disruption of tumor cell–intrinsic EP4 signaling may have systemic effects." (PMID 39298269, 2024). "This notion is supported by the finding that Ptger4-KO tumors with unaltered PGE2 synthesis enzymes, but decreased adenosine production by tumor cells, show a similar degree of tumor growth suppression." (PMID 39298269, 2024). "Flow cytometric analysis 10 days after implantation confirmed the decrease in adenosine-synthesizing enzymes CD73, CD38, and CD203 in tumor cells from both KO lines, while CD39 protein was unchanged in Ptger4-KO and decreased in Ptges-KO tumors." (PMID 39298269, 2024). "As for receptors for prostaglandins, according to the GEPIA portal, there is an elevated expression of PTGER4/EP4 and TBXA2R/TP in the tumor relative to healthy brain tissue, these two being receptors for PGE2 and TxA2, respectively." (PMID 36765904, 2023). "For example, high levels of DAB and PTGER4, two of the top upregulated genes in RBPMS clones, act as tumor suppressor genes." (PMID 36499073, 2022). "Other pairs of co-expressed genes encoding prostanoid receptors were as follows: PTGIR-PTGER2, r = 0.72 − 0.75, TGCT tumor; PTGER4-PTGER2, 0.68–0.78, SKCM tumor; PTGDR-PTGER2, r = 0.66 − 0.74, SKCM tumor; PTGDR-PTGER3, 0.59–0.67, PAAD tumor." (PMID 35453789, 2022). "PTGER4 is a major PGE2 receptor and is involved in the feed-forward pathway that upregulates STAT3 phosphorylation and activates PTGS2 expression in the tumor cells of CRC." (PMID 36142151, 2022). "To analyze the patterns of gene methylation in patients with CRC, we evaluated the methylation levels of PTGER4 and ZNF43 in both tumor tissue and adjacent normal tissue." (PMID 36142151, 2022). "We found that SLC1A5 and SPP1 are mainly produced by tumor cells while LGALS9 and PTGER4 are mainly expressed in TAMs." (PMID 36476645, 2022). "Our results show that PTGER4 functions as a tumour suppressor in selected GBM patients and regulation of its expression by DNA methylation predict response to PTGER4 activation therapy in 2D and 3D in vitro models." (PMID 34675201, 2021). "In animal studies, selective inhibition of the prostaglandin E receptor 4 (EP4), one of four PGE2 receptors, suppresses tumor growth, restoring the tumor immune response toward an antitumorigenic condition." (PMID 32210957, 2020).
tumor (continued). "The prostaglandin E2 receptor 4 gene (PTGER4) product, EP4, is important in tumor progression mediated by prostaglandin E2, which has been confirmed to have an upregulated expression in cancer tissues compared with that in normal tissues." (PMID 31888670, 2019). "A major target of their products seem to be TAMs, which express considerable higher levels of the PGE2 and PGI2 receptor genes PTGER2, PTGER4, and PTGIR with the exception of PTGER3 expressed only by a small subset of tumor cells." (PMID 27215396, 2016). "This is concordant with PGE2 being the major prostanoid in tumor microenvironments and fits previous observations in ApcMin transgenic mice, where deletion of PTGER1, PTGER2, and PTGER4 inhibits the development of CRC." (PMID 26207152, 2015). "The opposite trend was observed with PTGER4, PTGDS, PTGER3, PTGIS, PTGFR, and PTGS1 genes, which showed overexpression in the adjacent non-tumor tissue, followed by downregulation in the tumor." (PMID 26207152, 2015). "Thus, higher level of PTGER4 and EP4R may lead tumor cell to proliferate." (PMID 24069348, 2013). "This may be related to the binding of tumor cell-expressed OPN to macrophage PTGER4, as OPN can mediate crosstalk between tumor cells and macrophages through PTGER4, leading to macrophage polarization to the M2 phenotype." (PMID 40093009, 2025). "Similarly, deletion of Ptger4 in epithelial cells disrupts the regenerative reprogramming of ISCs and prevents SCA‐1+ cell proliferation and tumour initiation in ApcMin/+ mice." (PMID 38386338, 2024). "RNA-seq analysis of bulk Ptger4-KO tumors (but not in vitro– and in vivo–sorted KO tumor cells) indicated significantly decreased TGF-β signaling compared with the controls." (PMID 39298269, 2024). "PTGER4 is a G-protein-coupled receptor that mediates the action of prostaglandin E2 (PGE2), playing a crucial role in cancer cell proliferation, invasion, stem cell regeneration, and tumor angiogenesis." (PMID 37670284, 2023). "In this study, both PTGER4 and ZNF43 were classified as tumor-suppressor genes." (PMID 36142151, 2022). "Ptger4, which encodes murine EP4, was upregulated in debris-stimulated Panc02-H7 tumors compared to Panc02-H7 tumors derived from only living tumor cells (with no debris)." (PMID 34607951, 2021). "Moreover, genetic overexpression of PTGER4 in GIC18 negatively impacted the proliferation of the cells, in keeping with the interpretation that it has a tumour suppressive role in GIC." (PMID 34675201, 2021). "To assess the role of PTGER4 in endometrial cell tumorigenesis in vivo, we xenografted either WT cells or PTGER4 cells into the dorsal flanks of CD1-Foxn1nu mice and measured the resulting tumour growth over a 35 day period." (PMID 21589857, 2011). "Although we didn't find a correlation with hypoxia and VEGF between the WT and PTGER4 xenografts in our study, it is plausible that hypoxia can induce VEGF equally in both groups early on during tumour growth independent of PTGER4 when vascular networks are forming." (PMID 21589857, 2011). "Interestingly, we found that expression of PTGS2 but not PTGS1 was elevated in PTGER4 tumour xenografts compared with WT xenografts." (PMID 21589857, 2011). "Tumor tissue and matched adjacent nontumorous tissue were extracted from 208 patients with CRC, and the correlation between the methylation levels of PTGER4 and ZNF43 at certain CpG loci and the prognostic factors of CRC was determined using the MassARRAY System testing platform." (PMID 36142151, 2022). "Furthermore, PTGER4's negative correlation with immune checkpoints (PDCD1, CTLA4) underscores its potential to counteract immune exhaustion, a phenomenon critical for sustaining anti‐tumour immunity." (PMID 41284374, 2025).
tumor (continued). "In agreement with this hypothesis, higher expression of PTGER4 is observed in the tumour bulk of GBM18 and in the TCGA GBM cohort as compared to GIC18, and a negative correlation was observed between the expression of PTGER4 and PROM1 (CD133), a GIC marker, in the TCGA datasets." (PMID 34675201, 2021).
cancer (110 papers, 2006 to 2025). A tumor composed of atypical neoplastic, often pleomorphic cells that invade other tissues. "A clear association of CD44, PTGER4, and α4β1 in SN macrophages, plasma cells, cancer cells, and T cells was observed with upregulated SPP1 in macrophages." (PMID 37745301, 2023). "Our study aimed to couple photodynamically priming with antagonism of the prostaglandin E receptor 4, a therapeutic target linked to cancer-associated migration, invasion, angiogenesis, and immune evasion." (PMID 34771424, 2021). "Once LAB colonizes in GC, it can potentially promote GC via 4 mechanisms: 1) via impact the release of interleukin-1β/17 A/22, 2) via IL-17RC/NF-ᴋB/NOX1 pathway, 3) via gastric inflammatory and cancer-associated genes TNF-α/Ptger4/Tgf-β, 4) via N-nitroso compounds and 5) ROS." (PMID 38075398, 2024). "Comparison of the positivity rates of detecting SHOX2, RASSF1A, and PTGER4 gene methylation in cancer tissues and paracancerous tissues of LC patients (n (%))." (PMID 40386526, 2025). "The methylation positive rates of SHOX2, RASSF1A and PTGER4 genes in cancer tissues were 48.00%, 32.00% and 64.00%, significantly higher than those in para-carcinoma tissues (16.00%, 4.0%, 14.00%, P<0.05)." (PMID 40386526, 2025). "Most steps of the cancer immune cycle were highly activated in KIRC samples with high PTGER4 expression." (PMID 41284374, 2025). "Comparison of the expression of SHOX2, RASSF1A, and PTGER4 in cancer tissues and paracancerous tissues of LC patients (n (%))." (PMID 40386526, 2025). "PTGER4 is an early growth response factor-regulated gene located on chromosome 5p13.1, and the activation of this gene promotes the growth of cancer cells, which is often applied as a specific indicator for the early detection of cancer." (PMID 40386526, 2025). "The positive expression rates of SHOX2, RASSF1A and PTGER4 in cancer tissues were 44.0%, 54.00% and 50.00%, significantly lower than those in para-carcinoma tissues (90.00%, 96.00%, 82.00%, P<0.05)." (PMID 40386526, 2025). "Univariate Cox regression analysis of PTGER4 confirmed that PTGER4 was a protective marker in most cancer types." (PMID 41284374, 2025). "CYSLTR1 and PTGER4 are primarily expressed by immune cells in human cancers, while LTB4R, PTGER1 and PTGER3 are found in neuroendocrine and tuft cells." (PMID 37386128, 2023). "In the training group, the methylation levels of SHOX2 and PTGER4 in cancer patients were significantly higher than those in healthy controls (p < 0.05)." (PMID 31888670, 2019). "Both in vivo and in vitro, we observed that PGE2 potently induces mucus expression, which has previously been reported to be mediated by prostaglandin E2 receptor EP4 subtype (PTGER4)-mediated mucin exocytosis in a human carcinoma cell line." (PMID 31337664, 2019). "The expressions of SHOX, RASSF1A and PTGER4 proteins in cancer tissues and para-carcinoma tissues were detected by immunohistochemistry, and methylation status of SHOX, RASSF1A and PTGER4 genes in peripheral venous blood was detected by sulfite-modified real-time fluorescence quantification." (PMID 40386526, 2025). "The results of this study showed that the positive expression rates of SHOX2, RASSF1A and PTGER4 in cancer tissues of LC patients were significantly lower than that in paracancerous tissues, suggesting that low expression of SHOX2, RASSF1A and PTGER4 is common in LC patients." (PMID 40386526, 2025). "The methylation positivity rates of SHOX2, RASSF1A, and PTGER4 genes in cancer tissues of LC patients were 48.00%, 32.00%, and 64.00%, respectively, which were significantly higher than those in paracancerous tissues, which were 16.00%, 4.0%, and 14.00%, respectively (P < 0.05)." (PMID 40386526, 2025). "Besides, PTGER4 was significantly downregulated in cancer cells (logFC = −0.256) compared to non‐cancerous cells at the scRNA‐seq level." (PMID 41284374, 2025).
cancer (continued). "The positive expression rates of SHOX2, RASSF1A, and PTGER4 in cancer tissues of LC patients were 44.0%, 54.00%, and 50.00%, respectively, which were significantly lower than those in paracancerous tissues, which were 90.00%, 96.00%, and 82.00%, respectively (P < 0.05)." (PMID 40386526, 2025). "Receptors for eicosanoids in PRN and PRT cancer models are primarily located in immune cells and fibroblasts: Fpr2 is located in granulocytes, Cysltr1 and Ptger4 in macrophages (and B cells in PRT), Ptger3 in fibroblasts, while Ptgir is found in smooth muscle cells." (PMID 37386128, 2023). "In a transgenic INS-GAS mouse model, the gastric lesions instigated by the overgrowth of Lactobacillus murinus ASF361 were found to be correlated with the robust expression of molecules associated with gastric inflammation and cancer, including TNF-α, Ptger4, and TGF-β." (PMID 37583514, 2023). "The positive expression rates of SHOX2, RASSF1A and PTGER4, and positive rates of SHOX2, RASSF1A and PTGER4 genes methylation in cancer tissues and para-carcinoma tissues were compared." (PMID 40386526, 2025). "In order to better understand the mechanisms of cancer progression, some mediators (PTGS2 and PTGER4), which have been extensively studied by our research group previously, have been verified." (PMID 38891950, 2024). "However, of those genes included in the pPRS score, prior evidence links NSAIDs anti-cancer activity with β-catenin (CTNNB1), GNAS, and PTGER4, the extracellular receptor for PGE2 that is the major downstream prostanoid produced by PTGS-2." (PMID 40763299, 2025). "Increased CD44 and PTGER4 in many cell types such as macrophages, DCs, cancer cells, and T cells were correlated to upregulated SPP1 in macrophages; the activated interaction pairs were correlated to cancer immune escape and metastasis." (PMID 35874770, 2022). "We compared the expression of the 15 immune gene cancer tissues and adjacent tissues in the TCGA-BLCA cohort and found that the expression of the CCR9, IL7, PTGER4, IL10, CTSG, and ZBTB16 proteins in the adjacent tissues was significantly higher than that in the cancerous tissues (P < 0.05)." (PMID 32655621, 2020). "However in another study, treatment with GW501516, a PPARβ/δ agonist, enhanced prostaglandin E receptor 4 (EP4) expression and promoted NSCLC proliferation, demonstrating that PPARβ/δ activation may be a unique molecular strategy to control the development of human cancer." (PMID 35631448, 2022).
infection (17 papers, 2013 to 2024). The state of being infected such as from the introduction of a foreign agent such as serum, vaccine, antigenic substance or organism. "During the late stage of infection, higher protein levels of PTGER4 and WNK1 were detected in Alkbh5-deficient neutrophils." (PMID 35764614, 2022). "Since the effector function of PGE2 produced by myeloid cells depends on its binding to EP receptors, we studied gene expression of its 4 receptors, EP-1 (Ptger1), EP-2 (Ptger2), EP-3 (Ptger3) and EP-4 (Ptger4), in hearts of mice during infection." (PMID 26305786, 2015). "Previous studies have shown that PTGER4 transcript levels are significantly upregulated in oyster gills following pathogen attack, which is the same as our result at the onset of infection, further suggesting a role in the oyster’s defense response to bacterial pathogens." (PMID 38891754, 2024). "Ptger4-deficient cells outcompeted control cells in establishing the antigen-specific pool of CD8+ T cells in the LP and in the induced-IEL fraction, upon oral infection with LmOVA, whereas no such difference was observed in mLN." (PMID 38200005, 2024).
adenocarcinoma (8 papers, 2008 to 2025). A common cancer characterized by the presence of malignant glandular cells. "Stratification analysis revealed that the effects of these SNPs in PTGER4 and PRKAA1 on GC susceptibility were dependent on smoking and were associated with a reduced risk of adenocarcinoma (p < 0.05)." (PMID 37670284, 2023). "In this study, PTGER4 rs10036575 was found to be a protective factor in non-smokers and participants with adenocarcinoma." (PMID 37670284, 2023).
PTGER4 also shares sentences with these, for which no sentence is quoted: Arthritis (13 papers); osteoarthritis (10); myocardial infarction (8); Obesity (8); experimental autoimmune encephalomyelitis (7); liver fibrosis (7); non-small cell lung carcinoma (7); rheumatoid arthritis (7); Stroke (7); kidney diseases (6); cardiac hypertrophy (5); Hypertension (5); inflammation (5); ischemic heart diseases (5); ischemic stroke (5); myocardial ischemia (5); renal fibrosis (5); Cerebral ischemia (4); chronic kidney disease (4); ischemia (4); mesothelioma (4); oral cancer (4); skin inflammation (4); squamous cell carcinoma (4); Alzheimer disease (3); aortic aneurysm (3); B cell lymphoma (3); colorectal tumor (3); fibrosis (3); heart failure (3).
A further 174 diseases each share a sentence with PTGER4 in 3 papers or fewer.